TNF (tumor necrosis factor)
Diseases named in the same sentence as TNF in open-access papers (continued):
Sharing a sentence is not in itself a finding about the gene and the disease.
adenoma (continued). "However, the mRNA levels of tumor-associated genes, including Vegf-a, interleukin 6 (Il6), and tumor necrosis factor α (Tnfα), were comparable in all adenomas from Apcmin/+; Crhr1−/−, Apcmin/+; Crhr1+/−, and Apcmin/+; Crhr1+/+ mice." (PMID 33494263, 2021). "Furthermore, wogonoside dramatically decreased the secretion and expression of IL-1β, IL-6 and TNF-α as well as the nuclear expression of NF-κB in adenomas and surrounding tissues." (PMID 27102438, 2016). "As SOCS3 has been shown to inhibit the actions of IL-6 and TNFα in the intestine, we hypothesized that decreased SOCS3 expression in normal mucosa may predispose to adenomas and thus increase risk for CRC." (PMID 20500855, 2010). "Anti-TNFα treated mice also showed reduced numbers (34.3±4.49 adenoma, n = 8, P<0.0001, unpaired t test with Welsh correction) and sizes of polyps (1.516±0.022 mm in diameter, P<0.0001 unpaired t test with Welsh correction, n = 6) as compared to untreated APCΔ468 mice." (PMID 18698347, 2008). "Mild upregulation of G2M and Myc target pathways was also observed in adenoma, but KRAS signaling and TNF-alpha signaling were downregulated, in contrast to carcinoma (p < 0.003)." (PMID 37121965, 2023). "Interleukin-1β, IL-4, and TNF-α are overexpressed in early events of CRC development, such as hyperplastic polyps, adenomas, and serrated adenomas." (PMID 35884974, 2022). "The expression of IL-4, TNF-α, COX-2, and IL-1β is higher in serrated adenomas than in adenomas, but the expression of IL-10 shows the opposite trend." (PMID 35884974, 2022). "Analysis of TNF-α, CXCL1, IL-1β, IL-10 protein and TGF-β mRNA levels in colonic tissue segments devoid of obvious adenomas revealed the expected increases in these cytokines in the AOM/DSS mice were not affected by M(IL4) treatment." (PMID 34691050, 2021). "Thus, TNF-α (>5.9 pg/ml) may indicate the presence of adenomas with more advanced pathology." (PMID 24465801, 2014). "The increased number of Fn leads to elevated expression levels of cytokines IL-6, IL-10, IL-12, IL-17, and tumor necrosis factor-α (TNF-α), and the presence of mucosal inflammation may contribute to adenoma progression." (PMID 41019530, 2025). "Throughout progression from adenoma to carcinoma (A-CIA to C-CIA to CRC), there is a trend of decreasing abundances of cytotoxic T cells and TNF-α, coupled with increases of tumor, M2 macrophage markers, and immunosuppressive cytokines, suggesting that immune suppression continues to strengthen." (PMID 35379804, 2022). "Also, higher levels of pro-inflammatory cytokines, such as tumor necrosis factor-alpha (TNF-α) and interleukin-6 (IL-6), have been observed within adenoma tissues as an expression of an inflammatory state." (PMID 33182693, 2020). "Analyses of the proinflammatory cytokines TNF-α, IL-6, and IL-1β in the serum of participants with colorectal adenomas compared to non-adenoma controls revealed that the presence of adenomas do not lead to systemic elevation in the levels of these cytokines." (PMID 25884547, 2015). "We assessed the association between plasma endotoxin concentrations, plasma cytokines IL-4, IL-6, IL-8, IL-10, TNF-α, and interferon-γ (IFN-γ) levels, and local cytokine mRNA expression levels of IL-4, IL-6, IL-8, IL-10, IL-17, TNF-α, and IFN-γ in relation to adenomas." (PMID 23442743, 2013). "Median plasma or rectal mucosal cytokine levels were not different between cases and controls, with the exception of plasma TNF-α levels which showed a trend toward being higher in those with adenomas than those without adenomas (p=0.06)." (PMID 23442743, 2013). "The comparative proteomic data show that Ras, ERK, JNK, p38-MAPK and Akt, TNF and TGFb1, and MAPK and NFkB are the key nodes in their pathway networks; and that ERK/MAPK signaling is the significant canonical pathway in adenomas." (PMID 20426862, 2010).
adenoma (continued). "The nitroproteomic data of human pituitary adenomas show that TNF and IL1B are the key nodes in their pathway networks; and that p38-MAPK signaling is the significant canonical pathway that participates in an oxidative-stress response in an adenoma." (PMID 20426862, 2010). "In patients with non-functioning adenomas and pheochromocytomas, TNF α levels were similar to those detected in the control." (PMID 20640152, 2010). "After adrenalectomy, the levels of TNF α were decreased in patients with malignant tumors and in patients with Conn’s syndrome, nonfunctioniong adenomas and pheochromocytomas compared to the concentration before surgery." (PMID 20640152, 2010). "In patients with non-functioning adenomas and pheochromocytomas, TNF α levels were not significantly different from those of the control, (p > 0.05) and were respectively 11.0 ± 2.03 pg/mL; 9.14 ± 4.58 pg/mL." (PMID 20640152, 2010). "In our patients with malignant tumors of the adrenal cortex, in patients with Conn’s syndrome and in patients with non-functioning adenomas and pheochromocytomas the concentration of TNF α was decreased after adrenalectomy." (PMID 20640152, 2010).
cryptococcal infection (38 papers, 2009 to 2025). "These three intracellular cytokines were chosen for study due to their importance in host defenses against cryptococcosis (32, –, 35) and the loss of protection phenotype seen in vaccinated mice deficient in IFNγ, IFNγR, TNFα, or IL-23p19." (PMID 38980038, 2024). "In one study of 20 RA patients with cryptococcosis, increased risk was seen in patients with chronic kidney disease and those exposed to the anti TNF antibody, adalimumab." (PMID 31382367, 2019). "Mice with gene disruption of Th1-type cytokines, such as IFN-γ, IL-12, IL-18, and tumor necrosis factor alpha (TNF-α), are more susceptible to cryptococcal infections as compared with WT mice." (PMID 29518906, 2018). "TNFα signaling in the afferent phase of cryptococcal infection is associated with optimal DC activation and induction of Th1/Th17 polarization and protective immunity." (PMID 29403476, 2017). "Neutralization of IFN-γ, IL-12, and/or TNF-α in mice results in increased susceptibility to cryptococcal infection." (PMID 19727388, 2009). "Studies confirm that glucocorticoids, tumor necrosis factor-α (TNF-α) inhibitors, and calcineurin inhibitors substantially impair Th1-type immune responses and macrophage-mediated clearance, thereby significantly elevating the risk of cryptococcal infection." (PMID 41245252, 2025). "Despite the increased risk of developing cryptococcosis among patients using anti-TNF antagonists, a therapeutic option to evaluate in larger studies would be to target inhibition of TNF-α for the alleviation of the neurological symptoms associated with CM-IRIS, as suggested in two case reports." (PMID 29371546, 2017). "Anti-tumor necrosis factor alpha (anti-TNF-α) therapies have been increasingly used to treat inflammatory diseases and are associated with increased risk of invasive fungal infections, including Cryptococcus neoformans infection." (PMID 27406560, 2016). "M1 macrophages are induced by IFN-γ and TNF-α, functioning as the major fighters against cryptococcal infection by the following mechanisms." (PMID 41017910, 2025). "We focused on IFNγ, tumor necrosis factor alpha (TNFα), and interleukin (IL)-23 as these three cytokines have known benefit in murine models of cryptococcosis (32, –, 36)." (PMID 38980038, 2024). "Numerous murine and human studies have revealed IFNγ and TNFα are essential for host defenses against cryptococcosis (34, 39, 50, –, 52)." (PMID 38980038, 2024). "This well-established, protective effect of TNF-α in cryptococcal infections has recently been shown to involve TNF-α preprogrammed DC precursor cells to generate a protective response." (PMID 37998856, 2023). "CD8+ T cells also produce TNF-α and Th1 cytokines during cryptococcal infections, whereas CD4+ T cells secrete only Th2 cytokines." (PMID 37251371, 2023). "IL-12, IFN-γ, and TNF-α can protect against cryptococcosis, whereas a reduction in IL-2, IL-12, and IFN-γ can increase the risk of pulmonary and cerebral fungal infection." (PMID 37251371, 2023). "In cryptococcosis, TNF-α significantly promotes macrophage NO production and anti-cryptococcal activity." (PMID 36520787, 2022). "Our case should alert clinicians to the increased incidence and atypical presentation of pulmonary cryptococcosis in patients receiving anti-TNF-α treatment." (PMID 34401295, 2021). "M1 macrophages are regulated by STAT1 and are an early source of inflammatory cytokines and chemokines, such as IFN-γ, TNFα, IL-1, and IL-8, that drive the protective type 1 immune response against cryptococcosis." (PMID 33042164, 2020). "Tumor necrosis factor alpha (TNF-α) plays a critical role in the control of cryptococcal infection, and its insufficiency promotes cryptococcal persistence." (PMID 31404168, 2019). "In this study, we generated analogous C. neoformans strain engineered to express murine TNF-α with a goal to stimulate a protective response against cryptococcal infection." (PMID 31404168, 2019).
cryptococcal infection (continued). "Among 9 reported cases of cryptococcosis in CD patients, 6 had pulmonary cryptococcosis, and 2 cases had GI cryptococcosis as part of their disseminated disease during anti-TNF-α therapy." (PMID 30514241, 2018). "TLR2−/− and TLR4−/− mice produce similar levels of interleukin 1β (IL-1β), IL-6, IL-12p40 and tumor necrosis factor-α (TNF-α) compared to littermates during cryptococcal infection, and survival rates are similar compared to wild type (WT) mice." (PMID 29543719, 2018). "Collectively, these findings along with the temporal concordance support that the induction of protective Th1 and Th17 effector cells in the lungs is the most crucial aspect of TNF-α biological activity during cryptococcal infection." (PMID 27406560, 2016). "TNF-α is another cytokine that mediates protection during cryptococcosis." (PMID 36294634, 2022). "Thus, survival in HIV and cryptococcosis co‐infection is associated with higher expression of pro‐inflammatory cytokine responses (IFN‐γ, TNF‐α and IL‐6) and corresponding higher influx of white blood cells that infiltrate the cerebrospinal fluid." (PMID 32472727, 2020). "A study in a similar setting showed a wide spectrum of pro‐inflammatory protein profile (IFN‐γ, IL‐1β, TNF‐α) and anti‐inflammatory proteins (IL‐10, granulocyte monocytes/macrophage colony stimulating factor (GM‐CSF)) being upregulated in CSF during cryptococcal infection." (PMID 32472727, 2020). "Since TNFα production is essential in the immune response against cryptococcal infection, it is understandable that depleting TNFα with biologicals may facilitate development of cryptococcosis." (PMID 31382367, 2019). "Taken together, our results support that TNF-α expression by an engineered C. neoformans strain while insufficient to drive complete immune protection, strongly enhanced protective responses during primary cryptococcal infection." (PMID 31404168, 2019). "Thus, the effect of early TNF-α depletion on the polarization/activation of CD4+ T cells during cryptococcal infection needs to be accurately assessed." (PMID 27406560, 2016). "The precise effect of TNF-α in T cell polarization in cryptococcal infection remains unknown; thus, our first objective was to determine whether TNF-α is required for the development of a protective Th1/Th17 bias in C. neoformans-infected mice." (PMID 27406560, 2016). "This study identified critical interactions between cells of the innate immune system (DC), the emerging T cell responses, and cytokine networks with a central role for TNF-α which orchestrate the development of the immune protection against cryptococcal infection." (PMID 27406560, 2016). "Indeed, in murine cryptococcosis MCP-1 was shown to control the early production of pro-inflammatory cytokines such as TNF-α and IL-6, the recruitment of mononuclear cells to infected lungs and the immunoprotection mediated by Th1 immunity." (PMID 24205424, 2013). "Furthermore, delivery of a TNF-α-expressing adenoviral vector to C57BL/6 mice infected with C. neoformans 52D prevented Th2 development and promoted protective Th1 responses during cryptococcal infection, which was associated with improved pulmonary DC MHCII-maturation." (PMID 31404168, 2019). "Furthermore, the enhanced risks for cryptococcal infection in individuals undergoing anti-TNF-α therapies for sepsis, cancer, and autoimmune disorders provided strong evidence that this cytokine also plays an important role in mediating host defense against C. neoformans infection in human." (PMID 31404168, 2019). "The effect of TNF-α on DC polarization status in LALN during cryptococcal infection is unknown." (PMID 27406560, 2016). "Immunotherapy, including vaccines and mediators, such as TNF-α or IFN-γ, antibody-based treatment, and prophylaxis, are promising modalities for the prevention and treatment of cryptococcosis." (PMID 37251371, 2023).
cryptococcal infection (continued). "To test this, we quantified levels of seven cytokines and chemokines (interferon-γ (IFN-γ), TNF-α, interleukin-1b (IL-1b), interleukin-6 (IL-6), MCP-1, G-CSF and GM-CSF) in the media immediately following cryptococcal infection and again 18 hours later." (PMID 29596441, 2018). "Th1 cytokines, including tumor necrosis factor alpha (TNF-α), are critical for protective immunity and clearance of cryptococcal infection in mice." (PMID 28143979, 2017). "Collectively, these findings show that early TNF-α signaling is required for the local development of Th1/Th17 CD4+ T cell polarization in the lungs and a protective systemic immune response during cryptococcal infection." (PMID 27406560, 2016). "Protection against cryptococcosis is induced following the production of Th1-type cytokines including IL-12 and IFN-γ, as well as the pro-inflammatory cytokine TNF-α." (PMID 19727388, 2009). "Under the combined stimulation of cytokines such as IL-2, IL-12, IL-15 and IL-18, NK cells are capable of producing IFN-γ and TNF-α, which promote Th1 polarization of CD4+ T cells and M1 polarization of macrophages, enhancing systemic immunity against cryptococcal infection." (PMID 41017910, 2025). "Their roles include production of pro‐inflammatory cytokines, including IL‐6, TNF‐α and IFN‐γ,114 that may influence the extent of cryptococcosis‐induced inflammation, immune activation and host damage responses." (PMID 32472727, 2020). "The effects of early TNF-α signaling and/or its disruption on the DC polarization profile in the lungs and lung-associated lymph nodes (LALN) during cryptococcal infection have not been studied." (PMID 27406560, 2016). "Here, we report that early TNF-α signaling is responsible for the acquisition of a DC1 phenotype by LALN DC, which optimally activates and polarizes CD4+ T cells to the Th17 and Th1 lineage in the LALN during the afferent phase of cryptococcal infection." (PMID 27406560, 2016). "Using a mouse model of cryptococcal infection, we investigated the mechanism by which disruption of early TNF-α signaling results in the development of nonprotective immunity against C. neoformans." (PMID 27406560, 2016). "It was associated with a low peripheral CD4 count, reflecting the importance of cell-mediated immunity in controlling cryptococcal infection, and with a poor inflammatory response at the site of infection, as evidenced by low CSF white cell counts and low levels of IFN-γ, TNF-α, and IL-6." (PMID 24319084, 2014). "Neutralization of TNF-α reduced leukocyte influx to the lung and resulted in higher fungal burdens during a pulmonary infection of C. neoformans; TNF-α was required for the induction of IL-12 and IFN-γ, which mediated protection during a pulmonary cryptococcal infection." (PMID 36294634, 2022). "Severe cryptococcosis in the FcγRIIb−/− mice was demonstrated by high fungal burdens in the internal organs with histological cryptococcoma-like lesions and high levels of TNF-α and IL-6, but not IL-10." (PMID 28074867, 2017).